DHRS1 (dehydrogenase/reductase 1)
Description:
NADPH-dependent oxidoreductase which catalyzes the reduction of steroids (estrone, androstene-3,17-dione and cortisone) as well as prostaglandin E1, isatin and xenobiotics in vitro. May have a role in steroid and/or xenobiotic metabolism.
Synonyms: SDR19C1; FLJ25430; MGC20204
Tractability: Small molecule: it has a high-quality binding pocket. PROTAC: ubiquitination databases record sites on it; its protein half-life has been measured.
Gene: Protein-coding gene on chromosome 14 (24,290,598 to 24,300,136, reverse strand). Ensembl gene ENSG00000157379.
Subcellular location: Endoplasmic reticulum
Subcellular location (Human Protein Atlas): Nucleoplasm; Centrosome; Cytosol
Gene Ontology:
Molecular function: carbonyl reductase (NADPH) activity; oxidoreductase activity, acting on the CH-OH group of donors, NAD or NADP as acceptor; protein binding; estradiol 17-alpha-dehydrogenase [NAD(P)+] activity; testosterone dehydrogenase (NADP+) activity
Cellular component: endoplasmic reticulum
Genetic constraint (gnomAD): Loss-of-function variants: 36 observed, 39.56 expected, observed/expected ratio (o/e) 0.91, 90% interval 0.7 to 1.2. The upper end of that interval is the gene's LOEUF score, 1.2, which puts it in group 5 of 6, group 1 being the genes least tolerant of losing a copy. Missense variants: 354 observed, 425.65 expected, observed/expected ratio (o/e) 0.83, 90% interval 0.76 to 0.91. Synonymous variants: 133 observed, 169.45 expected, observed/expected ratio (o/e) 0.78, 90% interval 0.68 to 0.91.
Homologues: Orthologues: chimpanzee DHRS1 (99% identical), macaque DHRS1 (96% identical), rabbit DHRS1 (87% identical), rat Dhrs1 (85% identical), dog DHRS1 (83% identical), mouse Dhrs1 (83% identical), guinea pig DHRS1 (80% identical), pig DHRS1 (74% identical), zebrafish dhrs1 (58% identical), Caenorhabditis elegans dhs-9 (45% identical), Caenorhabditis elegans F59E11.2 (42% identical), Drosophila melanogaster CG31548 (13% identical), and 1 more. Paralogues in human: HSDL2 (23% identical), CBR3 (18% identical), CBR1 (18% identical), DHRS4 (16% identical), DHRS7B (15% identical), DHRS2 (14% identical), DHRS7 (14% identical), DHRS7C (14% identical), HSD11B1 (14% identical), RDH8 (13% identical), DHRS11 (12% identical), DHRS4L2 (12% identical), and 1 more.
Diseases named in the same sentence as DHRS1 in open-access papers:
DHRS1 is named in the same sentence as 4 diseases in open-access papers, as found by Europe PMC text mining. Sharing a sentence is not in itself a finding about the gene and the disease. The quoted sentences say what the papers report.
hepatocellular carcinoma (2 papers, 2023 to 2025). A malignant tumor that arises from hepatocytes. "Further, a connection between DHRS1 has been established in hepatocellular carcinoma, but not lung adenocarcinoma specifically." (PMID 40685627, 2025). "A member of the short-chain dehydrogenase/reductase superfamily (DHRS1, SDR19C1) is a member of the short-chain dehydrogenase/reductase superfamily and a potential predictor of hepatocellular carcinoma (HCC)." (PMID 37861541, 2023).
lung adenocarcinoma (1 paper, 2025). A carcinoma that arises from the lung and is characterized by the presence of malignant glandular epithelial cells. "Our results provide evidence of novel, sensible associations between CLN6 and DHRS1 expression and lung adenocarcinoma survival." (PMID 40685627, 2025).
cancer (1 paper, 2023). A tumor composed of atypical neoplastic, often pleomorphic cells that invade other tissues. "The cancer genome atlas (TCGA)-LIHC database was used to screen for immunomodulators associated with DHRS1, and we subsequently generated a prognostic model to predict the prognosis of HCC patients." (PMID 37861541, 2023).
tumor (1 paper, 2023). "We systematically analyzed the association between DHRS1 and HCC immunity with transcriptional and clinical data from the Tumor Immune Estimation Resource, an integrated repository portal for tumor immune system interactions, and cBioPortal databases." (PMID 37861541, 2023). "DHRS1 levels drop as the tumor stage and grade rise, indicating the potential involvement of DHRS1 in HCC." (PMID 37861541, 2023).